C19orf73 (chromosome 19 open reading frame 73)
Synonyms: FLJ10490
Tractability: No criterion of Open Targets' tractability assessment is met for any kind of drug.
Gene: Protein-coding gene on chromosome 19 (49,118,402 to 49,119,143, reverse strand). Ensembl gene ENSG00000221916.
Subcellular location (Human Protein Atlas): Cytosol; Nucleoplasm
Gene Ontology:
Molecular function: protein binding
Genetic constraint (gnomAD): Loss-of-function variants: 1 observed, 0.66 expected, observed/expected ratio (o/e) 1.52, 90% interval 0.32 to 1.92. That is too few expected variants to judge how well the gene tolerates losing a copy. Missense variants: 211 observed, 191.94 expected, observed/expected ratio (o/e) 1.1, 90% interval 0.98 to 1.23. Synonymous variants: 86 observed, 86.33 expected, observed/expected ratio (o/e) 1, 90% interval 0.84 to 1.19.
Homologues: Orthologues: chimpanzee C19H19orf73 (98% identical).
Diseases named in the same sentence as C19orf73 in open-access papers:
C19orf73 is named in the same sentence as 1 disease in open-access papers, as found by Europe PMC text mining. Sharing a sentence is not in itself a finding about the gene and the disease.
C19orf73 shares sentences with these, for which no sentence is quoted: ovarian carcinoma (1 paper).